ALB (albumin)
Diseases named in the same sentence as ALB in open-access papers (continued):
Sharing a sentence is not in itself a finding about the gene and the disease.
malnutrition (continued). "There was a significant association between serum Cr and malnutrition determined via a low GNRI, and there was a significant association between serum albumin and malnutrition determined via a low Cr index." (PMID 32238848, 2020). "Albumin is the body’s nutritional indicators, and low albumin usually indicates the body’s malnutrition." (PMID 33251247, 2020). "The ECW/TBW, known as the “oedema index”, is considered as one of the indicators of nutritional status—malnutrition leads to acute inflammation, decline in albumin level and oedema." (PMID 32660012, 2020). "The ALB levels < 32 g/L and CRP levels > 5 mg/L form part of the diagnostic criteria for malnutrition and cachexia." (PMID 33178828, 2020). "Nevertheless, the significance of low serum albumin is multiple, including malnutrition but also chronic inflammation (IL6-dependent liver synthesis), as well as haemodilution related to volume overload." (PMID 32792012, 2020). "In particular, hypoalbuminemia is not only a marker for malnutrition but also serves as an indicator for systemic inflammation, because the concentration of albumin can be exhausted by some pro-inflammatory substances, such as cytokines." (PMID 32000789, 2020). "In their study, serum endocan levels were inversely correlated with serum albumin levels, and patients with higher endocan levels had a lower subjective global assessment scale and a higher malnutrition-inflammation score." (PMID 33352837, 2020). "Malnutrition and cachexia also suppress the synthesis of serum albumin in advanced cancer patients as a result of tumor progression, the immune response to the tumor, and anticancer therapies." (PMID 33569000, 2020). "Low albumin has been shown to reflect malnutrition, which is common among patients with cancer, leading to disruption of a number of human defense mechanisms, such as anatomic barriers, cellular and humoral immunity, and phagocyte function." (PMID 32451768, 2020). "Compared to monoparasitism, dual parasitism was significantly associated with underweight (17.8 vs. 20.3 kg/m2), anaemia (7.7 vs. 9.8 g/dL), and malnutrition (27.6 vs. 31.9 g/L of albumin concentration)." (PMID 33029386, 2020). "ALB is a macromolecule with important physiological functions in animals, and malnutrition can lead to lower levels of ALB." (PMID 32645922, 2020). "Although serum albumin is often reduced in patients with malnutrition, the use of hypoalbuminemia is limited in the clinical settings because it is a result of malnutrition rather than a cause of it." (PMID 32218224, 2020). "Hemoglobin and albumin are indicators of human nutritional status; malnutrition is one of the important reasons for the development of STB." (PMID 32071918, 2020). "Albumin is a serologic marker of inflammation superimposed on malnutrition, which has inflammatory effects on the vascular endothelium and lipoprotein structure." (PMID 32370130, 2020). "Moderate malnutrition based on serum albumin levels classifications was higher in males while severe malnutrition was higher in females (P=0.408; P=0.198 respectively)." (PMID 33083290, 2020). "They indicated that hypoalbuminemia was a marker of malnutrition or systemic inflammation, because some proinflammatory substances, such as cytokines, reduced the concentration of albumin." (PMID 33215031, 2020). "The levels of albumin, prealbumin, total protein, and transferrin before and after treatment were used for assessing malnutrition." (PMID 32490516, 2020). "The utilization of nutritional support mixtures leading to clinical picture improvements in nutritional parameters, especially for increasing albumin-prealbumin concentrations, are effective in malnutrition management and attract interest from clinicians." (PMID 32213854, 2020). "The malnutrition group had a lower BMI, serum albumin, and BI score (p < 0.001), and a higher number of subsequent falls and a CCI (p < 0.001, p = 0.006, respectively) than the normal group." (PMID 32264913, 2020).
malnutrition (continued). "In this study, patients with PAD had significantly higher CRP levels and lower albumin, total cholesterol, and iron levels, which are indirect indicators of malnutrition, inflammation, and atherosclerosis syndrome." (PMID 31349820, 2019). "Low serum albumin was more greatly attributed to systemic inflammation than malnutrition in dialysis patients." (PMID 31731708, 2019). "Periodontitis, one of the major types of infection-driven inflammation, often co-occurs in the hemodialysis population and correlates with markers of malnutrition and inflammation, such as albumin, as well as creatinine and C-reactive protein." (PMID 31683838, 2019). "Preoperative serum albumin serves as an excellent tool to assess malnutrition and to predict patient outcomes and survival." (PMID 31253199, 2019). "A lower ALB level is related to the severity of inflammation or malnutrition, and has been proposed as a clinical tool for the estimation of hepatic insufficiency." (PMID 31821367, 2019). "For instance, serum albumin levels are generally altered in the presence of proteinuria, hypermetabolism, and malnutrition." (PMID 31615494, 2019). "In advanced tumor stages, the levels of serum albumin can drop sharply, because both malnutrition and systematic inflammatory response due to tumors suppress albumin synthesis." (PMID 31468203, 2019). "This is an important point in the development of malnutrition, and albumin can therefore be considered a nutrition marker." (PMID 31010007, 2019). "Malnutrition and inflammation were defined as low serum albumin (< 40 g/L) and high hs-CRP (≥ 28.57 nmol/L), respectively." (PMID 31048884, 2019). "GPS is a combination of CRP and albumin and is an exclusive index of systemic inflammation and malnutrition." (PMID 31096693, 2019). "As indexes to reflect the protein synthesis ability, low albumin and high globulin concentration in plasma indicate malnutrition or hepatobiliary disease." (PMID 31723184, 2019). "A recent meta-analysis suggested that several blood biomarkers, including albumin and hemoglobin, are useful for adult malnutrition evaluation." (PMID 30781460, 2019). "Malnutrition and hypoalbuminemia reduce antioxidant defense, and albumin and prealbumin, commonly used nutritional markers, possess antioxidant properties and can account for significantly lower FRAP values when compared with the controls." (PMID 31583040, 2019). "Studies have shown that serum albumin levels are one of the reliable predictors of malnutrition, and this phenomenon is closely related to clinical outcomes and are widely used as a tool for predicting morbidity and mortality." (PMID 30333517, 2019). "Serum albumin < 35 g/L is defined as malnutrition in previous studies, and this criterion is widely accepted by researchers." (PMID 31752900, 2019). "Malnutrition with hypoalbuminemia (albumin < 35 g/L) is an important factor in predicting risks associated with colorectal cancer surgery." (PMID 31253199, 2019). "It was reported that malnutrition assessed by serum albumin level was best predicted by hs-CRP level." (PMID 31048884, 2019). "In colorectal cancer, this is the first propensity score matching study of malnutrition with mild hypoalbuminemia which demonstrates that a mild decrease in serum albumin contributes significantly to poor postoperative outcome." (PMID 31253199, 2019). "Although establishing the degree of malnutrition in CD patients can be difficult, recent guidelines by ESPEN have defined severe malnutrition in CD as an Albumin <30 g/L, BMI <18.5 kg/m2 and weight loss >10–15% within six months." (PMID 31540038, 2019). "During malnutrition, protein synthesis by the liver is altered, resulting in low serum albumin levels, a functional measure of protein status." (PMID 31623146, 2019). "Inflammation has also been implicated in decreased iron bioavailability for erythropoiesis and low albumin levels, a sensitive marker of malnutrition." (PMID 31441929, 2019).
malnutrition (continued). "The predictive potential of serum albumin and the interplay between malnutrition and inflammation is well recognized and has been shown to strongly predict mortality." (PMID 31181128, 2019). "We observed a low value of serum albumin (<4.0 mg/dl; parameter of malnutrition) in 15 (35%) patients, and 22 (51%) patients had an ASA physical status classification system score of >2." (PMID 31012858, 2019). "In contrast, albumin levels were significantly lower in underweight subjects, and this finding was confirmed by other authors, making albumin a stronger biomarker of malnutrition, particularly in the setting of surgical outcomes." (PMID 30988354, 2019). "It has been reported that in the presence of chronic inflammation, malnourished patients have very low albumin levels, a sign of severity of malnutrition or a reflection of resistance to treatment." (PMID 31448023, 2019). "These authors proposed that a multidimensional approach including serological biomarkers such as albumin are needed to assess malnutrition in patients with dementia." (PMID 31159248, 2019). "When patients with acute illnesses were included, the predictive value of albumin and prealbumin was distinctly reduced, confirming the conclusion that they are more markers of inflammation than of malnutrition." (PMID 31159248, 2019). "Periodontitis, one of the major types of infection-driven inflammation, often co-occurs in the in the hemodialysis population and correlates with markers of malnutrition and inflammation, such as albumin, creatinine, and C-reactive protein." (PMID 31683838, 2019). "The prevalence of malnutrition was 18.7% using the MNA (long or short form), but it was greater if other diagnostic criteria were used (BMI, albumin, or weight loss) (45.7%)." (PMID 29710860, 2018). "NT-proBNP has recently been reported to correlate with inflammatory markers (interleukin-6 and C-reactive protein), a malnutrition marker (serum albumin), and protein-energy-wasting syndrome." (PMID 29457529, 2018). "Because cBMI does not reflect fluid accumulation, modified body mass index (mBMI, serum albumin × cBMI) is a more accurate measure of malnutrition status." (PMID 29545522, 2018). "As one of the most common markers for assessing nutritional status, the serum ALB levels fall sharply during cancer progression because both malnutrition and systematic inflammation can suppress ALB synthesis." (PMID 29568406, 2018). "The first thing to consider when interpreting our findings is the superiority between serum albumin and cBMI in representing patients’ malnutrition status." (PMID 29545522, 2018). "Biomarkers for malnutrition (albumin and transthyretin) and inflammation (CRP and α1-acid glycoprotein) were significantly associated with mortality in older men." (PMID 30249038, 2018). "The determination of some biochemical parameters (albumin, prealbumin and C-reactive protein) in patients with low scores subsequently makes it possible to confirm the status of malnutrition and to assess the degree of seriousness." (PMID 29922604, 2018). "A meta-analysis which included 2125 individuals demonstrated that even in the context which malnutrition was obviously observed, the serum albumin levels were normal." (PMID 30303998, 2018). "The problem is different if we consider the concentration of albumin for the diagnosis of malnutrition." (PMID 29710860, 2018). "The patient was evaluated confirming aphagia, emaciation (BMI=18.9) withsevere protein calorie malnutrition, sarcopenia, (serum albumin=2.9), vitamindeficiency and anemia." (PMID 29972409, 2018). "As kidney function deteriorates, HD patients experience both protein-calorie malnutrition and inflammation attack, decreasing albumin synthesis." (PMID 30149605, 2018). "Malnutrition and inflammation suppresses the synthesis of serum albumin, which can reflect the nutritional status of patients, as well as the severity, progression, and prognosis of disease." (PMID 29193777, 2018).
malnutrition (continued). "Recent studies have reported that NT-proBNP positively correlated with interleukin-6 and C-reactive protein and inversely correlated with serum albumin, so that NT-proBNP was considered a marker of inflammation or malnutrition." (PMID 29457529, 2018). "In our study, the markers of malnutrition and inflammation, albumin and WBC counts, were found to be similar between the RRF and non-RRF groups." (PMID 29510483, 2018). "Nevertheless, serum albumin of <3 g/dl is included as one of the best indicators of severe malnutrition in CD in the recent guidelines by ESPEN, in addition to a BMI < 18.5 kg/m2 and weight loss > 10–15% within six months." (PMID 30344603, 2018). "Albumin is the most common biomarker used to assess malnutrition, with albumin concentrations found to be lower in chronic stroke survivors than in age-matched nonstroke controls." (PMID 29568480, 2018). "This means that there is a limit to albumin as a marker of true malnutrition and interpretation of the medical implications of low serum albumin in PD patients." (PMID 30235860, 2018). "Inflammation was defined as those with hs-CRP ≥ 5 mg/L, while malnutrition was defined as those with serum albumin < 30 g/L." (PMID 30445969, 2018). "Nutritional markers are known to be as an important factor for survival in patients on PD, and among them, serum albumin concentration is often used as a surrogate measure of malnutrition." (PMID 29694445, 2018). "Wagner and Rombeau arbitrarily defined malnutrition in perioperative patients as a serum albumin level of less than 3.5 g/dl and/or unintentional weight loss of 15% of a patient's usual weight over 3 to 4 months." (PMID 30344603, 2018). "An albumin level below 35 g/dl is widely regarded as a threshold marker of malnutrition in older people." (PMID 29628887, 2018). "Serum albumin (ALB) level is closely related to the degree of malnutrition, so it is commonly used as an indicator of nutritional status." (PMID 29568406, 2018). "Serum albumin level is affected by inflammation and malnutrition; however, other studies found that it difficult to estimate." (PMID 30622957, 2018). "(B) Serum Angpt-2 concentration in relation to the presence (I+ ve: CRP ≥ 5 mg/L) or absence (I− ve: CRP < 5 mg/L) of inflammation and presence (M+ ve: albumin < 30 g/L) or absence (M+ ve: albumin ≥ 30 g/L) of malnutrition." (PMID 30445969, 2018). "Albumin level is a good tool to evaluate the nutrition status in cancer patients, and malnutrition is strongly correlated with worse treatment response and poor prognosis." (PMID 30258731, 2018). "Few studies have focused on the association between serum albumin by itself and prognosis of IgAN because serum albumin is usually thought of in connection with proteinuria or malnutrition or inflammation." (PMID 29795559, 2018). "The plasma concentration of prealbumin allows evaluation of acute PEM, while albumin is an indicator of long-term protein modifications, being significantly reduced only after extended periods of malnutrition." (PMID 29922604, 2018). "High-sensitivity C-reactive protein (hsCRP) is a prognostic factor for hepatocellular carcinoma (HCC), while albumin is known to be a disease severity index of the malnutrition status in HCC patients." (PMID 29880755, 2018). "Screening tools such as the Mini-Nutritional Assessment Short-Form (MNA-SF) were able to diagnose a nutritional problem before it manifested through changes in the biochemical markers of malnutrition (such as albumin or total protein)." (PMID 29710860, 2018). "Hypoalbuminemia can also reflect malnutrition severe enough to disturb the albumin synthesis capacity needed to maintain albumin homeostasis." (PMID 29298330, 2018). "Although patients with severe malnutrition received intervention from the nutrition support team, low serum ALB level at the time of admission was the important factor for inhibition of early discharge." (PMID 30305016, 2018).
malnutrition (continued). "UC patients with lower pre-surgical serum albumin, indicating malnutrition, were more likely to be readmitted." (PMID 30108206, 2018). "Albumin is the most commonly used blood biomarker for assessing malnutrition, followed by hemoglobin, total cholesterol, total lymphocyte counts, prealbumin, and total protein." (PMID 28771192, 2017). "PNI incorporates albumin and the peripheral blood lymphocyte count for identifying clinically relevant malnutrition and predicting short- and long-term postoperative outcomes." (PMID 28272344, 2017). "Hypoalbuminemia, often defined as serum albumin concentration <3.5 g/dL, is traditionally regarded as a standard indication of malnutrition." (PMID 28771192, 2017). "The degree of malnutrition (albumin), inflammation (CRP), arteriosclerosis (PWV), and fluid overload (BNP) were correlated well with the ECF/ICF ratio." (PMID 28099511, 2017). "After surgery, 16.5% (n = 14/85) of participants had malnutrition according to the BMI and almost half of participants (44.7%, n = 38/85) had low serum albumin levels." (PMID 28923097, 2017). "The levels of serum albumin (ALB) are closely related to the degrees of malnutrition, affected by inflammatory responses, and associated with a poorer prognosis in cancer patients." (PMID 29069861, 2017). "Albumin and globulin are major serum proteins, and low albumin and high globulin levels reflect not only malnutrition, but also a chronic inflammatory state in the body." (PMID 28187463, 2017). "Pre-albumin, a visceral liver-synthesized protein, is a sensitive marker for determining the state of malnutrition and easily quantified in hospital laboratories." (PMID 27906675, 2017). "Results from our meta-analysis showed that several blood biomarkers, including albumin, prealbumin, hemoglobin, total cholesterol, and total protein, are useful biochemical indicators of malnutrition, even with the presence of chronic inflammation." (PMID 28771192, 2017). "Instead, serum albumin level was more likely to be a measurement of disease severity than of malnutrition." (PMID 28420212, 2017). "Using serum albumin to assess the prevalence of malnutrition with cut-off point of 3.8–5.0 g/dl as normal and <3.8 g/dl for malnutrition, 32 (62.7%) of the malnourished children were categorized as normal." (PMID 28932602, 2017). "Albumin can reflect the nutritional status of patients with cancers; malnutrition is correlated with worse survival." (PMID 28886134, 2017). "In our study, the HRs of the quintile 1 and quintile 2 groups were attenuated after adjustment of serum albumin and hs-CRP concentrations, suggesting a possible association of low TG with malnutrition and inflammation and with mortality." (PMID 28549070, 2017). "Pre-albumin is a visceral liver-synthesized protein, which is sensitive to determining malnutrition." (PMID 27906675, 2017). "Nutritional parameters, including body mass index, serum albumin, dietary intake, normalized protein catabolic rate (nPCR), and malnutrition inflammation score (MIS), were measured at baseline." (PMID 28420212, 2017). "Concerning clinical data, the patient’s usual weight and current weight were correlated (|ρ| > 0.96), as well as the albumin level, the nutritional risk index (NRI) and malnutrition (|ρ| > 0.88)." (PMID 28282392, 2017). "We found that GNRI as a marker for malnutrition is sensitive to acute disease stress, due to its reliance on measures of albumin concentration." (PMID 28771192, 2017). "In our center, serum albumin is used to evaluate nutritional status when malnutrition is clinically suspected." (PMID 28114891, 2017). "This can be explained by the pathology of patients, which affects the values of albumin, cholesterol (which is synthesized by the liver), and lymphocytes (a parameter related to protein depletion and a malnutrition indicator)." (PMID 28549896, 2017). "Blood biomarkers, especially albumin, are often used for diagnosis of malnutrition in clinical practice." (PMID 28771192, 2017).